SETD2 (SET domain containing 2, histone lysine methyltransferase)
Diseases named in the same sentence as SETD2 in open-access papers (continued):
Sharing a sentence is not in itself a finding about the gene and the disease.
cancer (continued). "H3K36 tri-methylation by SETD2 has been linked to a plethora of critical pathways and processes, yet the functional implications of perturbed H3K36 tri-methylation by SETD2 mutations in cancer are still unclear." (PMID 30818762, 2019). "Serving as tumor suppressor genes in ccRCC, BAP1 and SETD2 mutations were related to worse cancer-specific survival." (PMID 30349421, 2018). "As loss of SETD2 is observed in a number of human cancer types, delineating the role of H3K36 methylation in cellular stress responses in both yeast and human cells will be of particular biological and clinical interest." (PMID 28903048, 2017). "In all cancers combined, there is a slight clustering of SETD2 missense mutations in an approximately 200 amino acid segment (p.M1468 up to p.Q1668) that overlaps with the SET domain." (PMID 27191891, 2016). "KDM5C or SETD2 in ccRCCs have been associated with advanced stage, grade and possibly worse cancer-specific survival." (PMID 26848523, 2016). "As SETD2 mutations are also seen in other cancer types, understanding the role of SETD2 in ccRCC will contribute to our understanding of these tumors." (PMID 27191891, 2016). "In this review we discuss the studies on the associated protein, Set domain containing 2 (SETD2), a histone modifier for which mutations have only recently been associated with cancer development." (PMID 27191891, 2016). "In the final part of the review, we focus on how loss of SETD2 function can contribute to cancer development." (PMID 27191891, 2016). "Across multiple cancers, most of the SETD2 alterations involved mutations and deletions but rarely amplification." (PMID 25611383, 2015). "Tumors with a widespread loss of DNA methylation were associated with mutations of the H3K36 methyltransferase SETD2, in contrast to methylation-low subgroups in other cancer types." (PMID 25473433, 2014). "Intriguingly, we find that enzymes that deposit histone marks associated with gene activation, such as the H3K4 trimethylases MLL1-4 and SETD1A/B, or the H3K36 trimethylase SETD2 are more often repressed and mutated in cancer." (PMID 25484917, 2014). "From all cancers on which SETD2 mutations have been reported, ccRCC shows the highest mutation rate." (PMID 24843002, 2014). "CcRCC is an example of a cancer, where a high rate of genomic alterations occurs in parallel to inactivating mutations and deletions of histone modifiers, such as SETD2." (PMID 24843002, 2014). "Consistent with this, SETD2 mutations were identified in a large variety of human tumors, suggesting that further studies are required to elucidate its role in repressing intragenic transcription initiation in the context of cancer." (PMID 40746737, 2025). "Our results regarding the susceptibility to ferroptosis of ccRCC cell lines highlight why SETD2 mutations may be advantageous in the evolution of the cancer." (PMID 40961184, 2025). "Although most mutations affecting SETD2 are monoallelic and may lead to haploinsufficiency, biallelic genetic defects in SETD2 and genetic translocations are found in different cancers." (PMID 39591760, 2025). "SETD2 deficiency disrupts this balance, resulting in hypermethylation or hypomethylation of histone proteins in vivo, which can induce malignant changes as cancer cells gain the ability to invade and migrate." (PMID 40959108, 2025). "In addition, it has been shown that cancer-associated mutations in SETD2 also concern resistance to chemical inhibitors such as Sunitinib, a tyrosine kinase inhibitor commonly used in targeted therapeutics for the treatment of metastatic RCC." (PMID 39591760, 2025). "Due to the high mutation rate of SETD2 in various cancer types, SETD2 may serve as a biomarker for ICB treatment, and a large population of patients may benefit from immunotherapy." (PMID 40102418, 2025). "Indeed, SETD2 was identified as one of the most mutated genes in a saturation analysis of 21 cancer types." (PMID 40462961, 2025).
cancer (continued). "Cancer gene databases have identified four mutation hotspots in the SETD2 gene." (PMID 39591760, 2025). "However, determining the downstream consequences for SETD2 mutations in each cancer type will be important as death by ferroptosis will depend on other pathways involved." (PMID 40961184, 2025). "Given that inducing ferroptosis is a potential therapeutic strategy for targeting tumors and that SETD2 is frequently mutated in cancer, we asked whether SETD2 loss may render some cancers resistant to ferroptosis." (PMID 40961184, 2025). "Similarly, a promising area of investigation in SETD2-mutated cancer is into immune checkpoint expression, such as HAVCR2, CTLA-4, or TIGIT or biomarkers such as CDCP1 and AXL." (PMID 41228333, 2025). "As Set2 homologs in human cells (i.e., NSD1, NSD2, NSD3 and SETD2) are frequently mutated in human cancers, these findings may have important implications in carcinogenesis and chemotherapy resistance." (PMID 38673978, 2024). "In addition, whole-exome sequencing studies have unveiled somatic mutations in the SETD2 gene across various malignant tumors; this suggests that SETD2 inactivation is linked to tumorigenesis in these organs, even if less frequently." (PMID 38611113, 2024). "SETD2 deficiency is associated with cancer occurrence and progression." (PMID 38843391, 2024). "Moreover, elevated SETD2 expression is significantly associated with poorer prognosis, lower overall survival (OS), and decreased cancer-specific survival (CSS)." (PMID 38611113, 2024). "Additionally, preclinical studies of WEE1 inhibition with adavosertib (also known as AZD1775) have demonstrated a synthetic lethal effect in SETD2-deficient cancers in cell lines." (PMID 38920407, 2024). "The protein expression of SETD2 is associated with better cancer-specific survival in mRCC." (PMID 38386122, 2024). "Similarly, studies on the CpG Island methylator phenotype (CIMP+) have highlighted the association of SETD2 and DNA methylation in cancer, with gene body hypomethylation and promoter hypermethylation which is in line with our results." (PMID 37528416, 2023). "Given that Setd2 deficiency activates oncogenic transcriptional output to promote tumorigenesis, we reason that SETD2-deficient cancer may be more sensitive to inhibitors of transcription." (PMID 36810256, 2023). "Furthermore, we uncovered mechanism-based therapeutic strategies for SETD2-deficient cancers through inhibition of histone chaperones and transcription elongation." (PMID 36810256, 2023). "Previously, association of SETD2 with DNA methylation has been shown in 4 cancer types." (PMID 37528416, 2023). "Fourth, a SETD2 mutation rate greater than 5% was found in 10 cancer types, indicating that a large population of patients may benefit from ICI treatment." (PMID 37479966, 2023). "SETD2 is frequently mutated in cancer, however, the functional impact of SETD2 loss and depletion on DNA methylation across cancer types and tumorigenesis is currently unknown." (PMID 37528416, 2023). "A genome-wide transcript profile for SETD2-deficient primary ccRCC tumors demonstrated that altered splicing patterns or splicing defects, including intron retention and variation in exon utilization, are widely present in SETD2-deficient cancers." (PMID 37025591, 2023). "Deficiency of SETD2 has been implicated in tumorigenesis in several other cancers." (PMID 38036730, 2023). "The incidence of SETD2 inactivating mutations in cancer is highest in ccRCC." (PMID 37604811, 2023). "In addition, somatic variants in SETD2 have been found in many different cancers such as breast cancer, leukemia, and renal neoplasia." (PMID 37372360, 2023). "This is in line with our results above which suggest that SETD2-dependent methylation changes contribute to gene expression changes in cancer-associated genes, which could be a contributing factor in cancer etiology." (PMID 37528416, 2023).
cancer (continued). "Mono-allelic and bi-allelic mutations in SETD2 are observed in many cancers, including ccRCC." (PMID 37025591, 2023). "For more detailed information about SETD2 mutations in cancer we refer to other resources." (PMID 35661267, 2022). "Mechanisms causing CIMP are heterogeneous, including mutations in IDH1/2 and SETD2 that were previously reported in specific cancer types, as well as reported for the first time here in new cancer types; the novel overexpression of BORIS/CTCFL spanned several cancer types." (PMID 35134107, 2022). "Notably, if read-through induced silencing indeed depends on H3K36me3/SETD2 in human cells, then it will be interesting to consider how exactly read-through transcription in SETD2 deficient cancer cells interferes with downstream genes." (PMID 35661267, 2022). "Besides direct SETD2 loss or mutation, SETD2 function can also be affected in cancer through mutations in histone H3." (PMID 35661267, 2022). "It will therefore be interesting to determine whether an increase in cell size also occurs following mutational inactivation of SETD2 in cancer cells." (PMID 36052643, 2022). "The increased OXPHOS activity of cancer cells induced by SETD2 deletion in RCC may also be associated with the PGC1α mediated metabolic network, which is consistent with the high SETD2 mutation rate found in the high-risk group." (PMID 36591111, 2022). "Interestingly, a pathogenic point mutation observed in cancer (R2510H) in the SRI domain of human SETD2 impairs its ability to methylate α-tubulin at lysine 40 during mitosis, whereas global methylation of H3K36 is unaffected by this mutation." (PMID 36052643, 2022). "Other than the seven previously reported cancer types presenting significant mutations in either IDH1 or SETD2 in the high-methylation group, we found four additional cancer types with small groups of patients whose mutational status significantly correlated with the increased CIMP score." (PMID 35134107, 2022). "Moreover, TMB was significant different among SETD2 truncating mutant cancer (2.2,1.–10.2), SETD2 missense mutant cancer (9.4, 2.3–39.5), and cancer with multiple mutations (118.1, 21.2–270.7)." (PMID 34127768, 2021). "Among all cancers with SETD2 mutations, ccRCC shows the highest mutation rate." (PMID 34715919, 2021). "Depending on the cellular micro-environment H3K36me3 may help to established de novo DNA methylation via DNMT3A/B or decreased level of SETD2 can also be associated with increased DNA methylation at intergenic regions in disease condition such as, cancer." (PMID 34663428, 2021). "SETD2 is an important epigenetic gene encoding histone methyltransferase SETD2 protein which is involved in gene transcription extension and mismatch repair, and the inactivation of SETD2 may contribute to cancer development." (PMID 34895266, 2021). "The unique features of SETD2 mutation makes it a potential biomarker for cancer immunotherapy." (PMID 34127768, 2021). "Interestingly, in addition to PDGFRA we found four genes previously shown to be driver mutations in different cancers: SETD2, FAT4, TRIP11 and PPP3CA (highlighted genes)." (PMID 32603362, 2020). "H3K36me3 is frequently lost in multiple cancer types, and this may be caused by loss of the tumor suppressor SETD2 and overexpression of KDM4A (a H3K36me3 demethylase)." (PMID 31590683, 2019). "In the remainder of this review we will discuss how the loss of or decrease in H3K36me3 caused by functional loss of SETD2 could contribute to cancer development." (PMID 27191891, 2016). "Moreover, the Cancer Genome Atlas database (TCGA) reveals co-mutation of PBRM1 and SETD2 in multiple tumors despite the low mutation frequency of both genes in these cancers." (PMID 27191891, 2016).
cancer (continued). "As global DNA hypermethylation was consistently induced in our models of SETD2 inactivation and in primary SETD2 mutant ccRCCs, we next investigated whether inactivating SETD2 mutations in other cancer types are associated with a hypermethylation signature." (PMID 26646321, 2016). "In the TCGA, SETD2 mutations were found to be associated with worse cancer-specific survival (P = 0.036; HR 1.68; 95% CI 1.04-2.73), and the presence of SETD2 mutations was a predictor of ccRCC recurrence in an univariant analysis (P = 0.002; HR 2.5; 95% CI 1.38-4.5)." (PMID 27191891, 2016). "Therefore, the selectivity of TGX221 for both VHL and SETD2 implies an inherent connection between those common mutations in a variety of cancers." (PMID 25853938, 2015). "It will be important to determine how loss of Setd2 affects the distribution of DNA methylation in the germline and soma, and whether loss of Setd2 contributes to aberrant methylation in cancer." (PMID 25848745, 2015). "The selective and potent killing of SETD2-deficient cells by AZD1775 suggested that AZD1775 could potentially be used to treat H3K36me3-deficient cancers." (PMID 26602815, 2015). "However, many people with this type of cancer have mutations in the gene for a protein called SETD2." (PMID 24843002, 2014). "SETD2-mutated cancers may be more sensitive to radio- and immunotherapy." (PMID 41228333, 2025). "As G12C is the most common KRAS oncogenic variant in LUAD, we used a recently developed KRASG12C-driven LUAD mouse model (named KcP) to test whether the additional loss of SETD2 (named KcP;Setd2) impacted cancer pathogenesis in vivo like it does in a G12D oncogenic mutant background." (PMID 40462961, 2025). "These elevated H3K36me3 may not only caused by SMYD5 but also SETD2 in cancer tissues." (PMID 35680905, 2022). "Indeed, in an analysis of The Cancer Genome Atlas (TCGA) pan-cancer cohort found that patients with tumors harboring SETD2 mutations responded favorably to treatment with immune checkpoint inhibitors, raising the possibility for targeted therapies in SETD2-mutated cancers." (PMID 34925233, 2021). "Although additional studies are needed to elucidate the biological importance of SETD2 mutations in MDS, our data provided insights into the role of SETD2 in MDS and suggested that this gene may be a novel therapeutic target in MDS, as well as other human cancers with SETD2 deficiency." (PMID 32849799, 2020). "However, an equally important area will be to understand the impact of increased SETD2 levels on the cellular landscape and how these epigenetic alterations may promote viral persistence, a major risk factor for the development of cancer." (PMID 30312361, 2018). "Alternatively, many studies on BAP1 or SETD2 have been conducted in other cancers and need to be confirmed in ccRCC." (PMID 41602827, 2026). "Sometimes, low expression of SETD2 can confer advantages of proliferation, colony formation, migration and invasion for cancer cells." (PMID 40959108, 2025). "Herein, we provide a review of the role of SETD2 in different cancers with special emphasis on the structural basis of the functions of this key lysine methyltransferase." (PMID 39591760, 2025). "Together, these findings provide insight into how SETD2 integrates histone modification signals to regulate H3K36 methylation and highlights the potential role of SETD2-associated epigenetic crosstalk in cancer pathogenesis." (PMID 40462961, 2025). "In the following paragraphs we describe the role of SETD2 in cell proliferation and migration, and the pathological consequences of this involvement, particularly in cancer." (PMID 39591760, 2025).
cancer (continued). "However, our work provides insights into how SETD2 mutations may contribute to cancer evolution through resistance to ferroptosis and NK cell evasion, and this will be important to consider in the context of ferroptosis inducers as cancer treatments." (PMID 40961184, 2025). "SETD2, the only known methyltransferase catalyzes the trimethylation of histone H3 lysine 36 (H3K36), has been reported to be associated with several cancers." (PMID 39668826, 2024). "LF1 levels were associated with somatic cancer driver mutations in PBRM1 and SETD2, chromatin remodelling genes linked to cell senescence and proliferation, which appears consistent with our observation that higher mitotic rates are related to these features." (PMID 39592856, 2024). "The discovery of six amplified (i.e., WHSC1L1, CCND1, and SOX2) and 29 deleted (i.e., NCOR1, SETD2, and CBL) cancer associated genes was highlighted." (PMID 38539567, 2024). "We will illustrate how MCDHGN demonstrates biological interpretability in predicting cancer driver genes by presenting case studies on the SETD2 and ZBTB17 genes." (PMID 38867699, 2024). "SETD2 expression in various human cancers was also examined using pancancer RNA-seq data from The Cancer Genome Atlas (TCGA) database." (PMID 39668826, 2024). "Neutrophils in the cancer environment can impede CD8+ T cell-dependent immune surveillance through various mechanisms, including Kras mutation, SETD2 deficiency-induced H3K36me3 methylation, miR-146a delivery, and the production of NO, GM-CSF, and arginase-1." (PMID 39034411, 2024). "Preclinical data showed that SETD2 is required for HRR, however we observed unimpaired HRR in certain types of cancers in SETD2 deleterious mutant samples." (PMID 37479966, 2023). "Overall, our studies not only provide insight into how SETD2 loss shapes the epigenetic and transcriptional landscape to promote tumorigenesis, but they also identify potential therapeutic strategies for SETD2 mutant cancers." (PMID 36810256, 2023). "With current innovations in genome engineering and proteomics, the role of SETD2 in normal cells and cancer will be better understood at the molecular level." (PMID 37025591, 2023). "We subsequently explored the association of PGAM1 mutations with common cancer progression genes, such as VHL, PBRM1, and SETD2." (PMID 37847178, 2023). "In our study, we found a parallel tendency of a TMB increase between SETD2 deleterious mutations and DDR gene mutations including BRCA1/2, MMR genes, and POLE/D1 across seven cancer types." (PMID 37479966, 2023). "PRCC also displays mutations in previously studied cancer-related pathways; these include NF2 (Hippo pathway), SMARCB1 and PBRM1 (SWI/SNF complex), and chromatin modifier pathways (SETD2, KDM6A, and BAP1)." (PMID 38162463, 2023). "The most frequent mutations in a large panel of 1123 cancer-related genes in the overall population of RCC patients were VHL (51%), PBRM1 (35%), BAP1 (16%), KMT2D (15%), PTPRD (15%), and SETD2 (15%)." (PMID 37427096, 2023). "We used the Cancer Therapeutics Response Portal (CTRP) database and found that SETD2 was associated with many targeted drugs, such as sorafenib, axitinib, sunitinib, and erastin." (PMID 37604811, 2023).